TNF (tumor necrosis factor)
Diseases named in the same sentence as TNF in open-access papers (continued):
Sharing a sentence is not in itself a finding about the gene and the disease.
liver cancer (continued). "The ethyl acetate extracts of Sappan lignum demonstrated the ability to induce cell cycle arrest at the G2/M phases and cell mitosis in lung, colon, and liver cancer cells in vitro while also inhibiting tumor necrosis factor-alpha/nuclear factor kappa-B cellular signaling to exert antitumor effects." (PMID 39318781, 2024). "It was found in the study that ginger extract (100 mg/kg body weight) suppressed the increased levels of tumor necrosis factor α (TNFα) and nuclear factor kappa B (NFκB) in rats that had liver cancer thus expressing both anticancer and anti-inflammatory potential." (PMID 39199328, 2024). "In the HepG2 liver cancer cell line, TNF-α upregulates MAT2B mRNA through AP-1 and NF-κβ pathways." (PMID 39353892, 2024). "It was previously reported that SOR reduces TNF-α and IL-16 levels in liver cancer in vitro." (PMID 37259369, 2023). "The result shows that the injection of HDW could significantly reduce the liver lesion area and the serum levels of IL-6, IL-17, TNF-α, and IL-1β in the orthotopic liver cancer mouse model, and these results were dose-dependent to some extent." (PMID 36647454, 2023). "The relevance of this phenomenon for treatment of liver cancer remains unclear due to the controversial role of TNF in cancer, exerting both pro- and anticarcinogenic effects." (PMID 36555597, 2022). "Its anti-cancer activity in HCC was not fully understood, but research owes its anti-cancer activity to decreased growth of liver cancer cells, caspase-dependent induction of liver cancer cells apoptosis, and inhibition of TNF-alpha induced inflammation in HCC." (PMID 36081339, 2022). "TGR5 receptors have many different agonists, but DCA and LCA are effective components that are able to inhibit tumor necrosis factor-α production in CD14+ macrophages by increasing the cAMP content to regulate NF-κB-p65 activation in the macrophages of liver cancer cells." (PMID 34885648, 2021). "It has been reported that TNF serves a critical role in the development of liver cancer." (PMID 32382293, 2020). "Furthermore, we detected HIF-1α and HMGB1 protein levels in SMMC-7721 and Huh7 human liver cancer cells after TNF-α (10ng/mL) treatment." (PMID 32328193, 2020). "The results showed that both the aqueous and ethanol extracts (QC and QS, respectively) of Qizhu decoction significantly inhibited hepatic inflammation and liver cancer induced by diethylnitrosamine or hepatitis B virus by suppressing NF-κB signaling and decreasing the levels of TNF-α and IL-1β." (PMID 30723284, 2019). "Appropriate control of the TNF signaling pathway and intestinal bacterial flora may help suppress inflammation of the liver and, ultimately, the occurrence of liver cancer." (PMID 30301191, 2018). "The role of TNF-α in liver cancer looks as a mixed blessing." (PMID 25197311, 2014). "Interestingly, the experimental rats with liver cancer induced by Diethylnitrosamine injection further confirmed the upregulation of miR-141 level, IL-10, and TNF-α and the disturbance in KLK10 and TNFSF-15 gene expression compared with their expression in normal rats." (PMID 38866875, 2024). "Similarly, a study of the lncRNA Highly Upregulated in Liver Cancer (HULC) showed that restoring HULC expression could rescue TNF-induced apoptosis, and that HULC regulates TNF-induced apoptosis by regulating miR-9 expression." (PMID 33558499, 2021). "Additionally, a previous work in a rat liver cancer model demonstrated that TNFα inhibition and deletion could decrease tumor incidence and showed that clinically TNFα expression was correlated to hepatic progenitor cells activation and HCC recurrences." (PMID 32256215, 2020).
liver cancer (continued). "The present study shows that exposure of liver cancer cell lines to an EVOO extract particularly enriched in LA (67%) and OC (32%) results in inhibition of cell proliferation that is associated with induction of autophagy and that can be potentiated by the pro-inflammatory cytokine TNFα." (PMID 31653043, 2019). "IL-6, STAT3, TNF-α and NF-κB are reported to play a central role in inflammation and control the expression of an array of growth factors and cytokines that may involve in hepatic cancer development." (PMID 27760163, 2016). "Wogonin supplementation is believed to reduce cytokines such as IL‐6 and TNF‐ and reduce PPAR‐mediated phosphorylation that subsequently decreases the viability of RAW264.7 cells in liver cancer conditions." (PMID 41164269, 2025). "Animal models show that pro-inflammatory cytokines, such as lymphotoxin-α, tumor necrosis factor-α (TNF-α), and interleukin-6 (IL-6), promote liver cancer and aggressive tumor traits." (PMID 41041128, 2025). "The expression of inflammation-related marker TNF-α, EMT-related marker ACTA2, and proliferation marker Ki67 was approximately 25-fold, 3-fold, and 2-fold higher in patient-derived liver cancer organoids, respectively, compared to normal liver organoids." (PMID 40852642, 2025). "IL-17 promotes liver cancer cell migration and invasion by increasing the levels of IL-8, MMP2, and VEGF, while TNF-α exacerbates liver cell injury and apoptosis via the NF-κB pathway." (PMID 40308492, 2025). "We treated liver cancer cells with the pyroptosis inducers LPS and nigericin (Nig), CHX and TNFα, and found that these inducers markedly induced cell death, exhibiting typical pyroptotic morphology." (PMID 38178583, 2024). "The varied expression levels of DEFRGs between the tumor and control groups in the TCGA-LIHC liver cancer dataset were compared, where ZFP36, NCOA4, FTH1, FTL, TNF, and PCBP1 were matched with the TCGA transcriptome data." (PMID 37555866, 2023). "Zuogui Pill can improve different clinical symptoms in treating liver cancer, by regulating multiply targets like PTGS2 and FOS, participating in MAPK, IL-17 and TNF signaling pathways." (PMID 37861529, 2023). "Co-culture of PD-L1-expressing mouse liver cancer cell line BNL-MEA with CD8+ T cells reduced the proliferation of T cell and the expression of interferon γ (IFN-γ) and TNF-α." (PMID 38155974, 2023). "In particular, we investigated the impact of IL-1β, IL-6, TNF-α, and TGF-β on PLIN5 expression in different human liver cancer cell lines." (PMID 37108378, 2023). "To verify the regulation of Iso2 on TNF and T cell numbers, we overexpressed Iso2 in two liver cancer cell lines (Huh7 and LM3) and detected elevated TNF-α by elisa." (PMID 37047287, 2023). "AFP is a tumor biomarker of liver cancer, serum ALT and AST levels are characteristic indexes reflecting liver function, and tumor necrosis factor TNF-α is an important inflammatory factor." (PMID 36110518, 2022). "The levels of liver cancer biomarker AFP, liver injury indicators ALT, AST and pro-inflammatory factor TNF-α in serum of rats treated with LFE were significantly lower than those in model group and close to blank group." (PMID 36110518, 2022). "The complex interaction of different proinflammatory factors (such as interleukin-6 or TNF-α) with anti-inflammatory cytokines (TGF-α and TGF-β) and their signaling pathways is involved in the occurrence and development of liver cancer." (PMID 35027925, 2022). "CD8+ T cells are the main TILs in liver cancer and can release perforin and granzyme B through the Fas/FasL pathway or kill target cells by releasing IFN-γ and TNF." (PMID 34335575, 2021).
liver cancer (continued). "In fibroblasts, TGF-β promotes fibrosis, while TNF-α is anti-fibrotic; in liver cancer Huh7 cells, TGF-β induces EMT, while TNF-α resists EMT." (PMID 35069596, 2021). "In terms of liver cancer, TGF-β treatment can induce Huh7 in liver cancer cells to up-regulate autophagy gene expression, strongly activate autophagy and induce EMT, while TNF-α inhibits TGF-β-induced EMT levels by inhibiting autophagy." (PMID 35069596, 2021). "Knock-out of TNFα or TNFR1 also reduced leukocyte infiltration and increased resistance to tumour development in mouse models of skin and liver cancer." (PMID 32325966, 2020). "Cytokines such as TNF-α, IL-6, and IL-1β can increase CD55 expression in liver cancer cells." (PMID 40596619, 2025). "In liver cancer, elevated ADA is correlated with serum atezolizumab concentrations and impaired functions of CD8-positive T cells, including suppressed secretion of interferon-γ and tumor necrosis factor-α." (PMID 39445019, 2024). "Besides, accumulating evidences have demonstrated that paeonol and forsythoside A, the effective components in JJJG, can act on the key pathological mechanism of (IL-6, TNF-α, IL-1β)/JAK2/STAT3/VEGF in the treatment of liver cancer and acute lung injury." (PMID 39494342, 2024). "In addition, the expression of PD-L1 induced by TNF-α and IFN-γ promoted the growth of liver cancer." (PMID 38155974, 2023). "In our study we observed that DENA increased TNF-α levels and downregulated the expression of the TRAIL receptors (DR4 and DR5) in liver cells, leading to the establishment of a higher necrosis level and, consequently, to the induction of liver cancer." (PMID 36276098, 2022). "The results showed that TNFα was not expressed in the xenografts from two groups, and knockdown of HK2 did not regulate the expression of TNFα in liver cancer cells." (PMID 35603967, 2022). "Both anti-CD8–anti-PD1 and anti-TNF–anti-PD1 antibody treatments ameliorated liver damage, liver pathology and liver inflammation, and decreased the incidence of liver cancer compared to anti-PD1 treatment alone." (PMID 33762733, 2021). "Meanwhile, the cytotoxicity of NK cells was enhanced through the inhibition of HMBOX1 via specific binding between miR-30c-1 and 3' UTR of HMBOX1, which leads to the increased expression levels of TNF-α(transmembrane TNF-α, mTNF-α) and repressed liver cancer progression." (PMID 32201529, 2020). "The data here reported clearly rule out the possibility that the increased cytotoxicity occurring in liver cancer cell lines exposed to the combined action of EVOO extract and TNFα might derive from enhanced oxidative stress." (PMID 31653043, 2019). "Overall, our data suggests that upregulation of TNF-α, P65 and IL-6 may reduce the PXR levels thereby influencing its cellular functions in hepatic cancer tissues." (PMID 27760163, 2016). "The expression of TNF-α and P65 (NF-κB) were enhanced to about 3.0 fold and 2.66 fold respectively at transcript level, while about 3.0 fold and 2.0 fold enhanced respectively at protein level in DEN-induced hepatic cancer as compared to control mice." (PMID 27760163, 2016). "The cytokine tumor necrosis factor (TNF)‐related apoptosis‐inducing ligand (TRAIL) induces apoptosis in liver cancer cells but not in normal liver cells." (PMID 27580702, 2016). "A significant decrease in serum TNF-α and IFN-γ levels were observed in liver cancer control group (group III), suggesting that decreased serum TNF-α and IFN-γ levels was an important marker of liver cancer." (PMID 22754316, 2012). "For instance, high BMI boosts Interleukin-6 and tumor necrosis factor production, triggering hepatic inflammation and activating the oncogenic transcription factor STAT3 (signal transducer and activator of transcription 3), thereby driving liver cancer progression." (PMID 40717954, 2025).
liver cancer (continued). "Safranal, the main bioactive component of saffron, can significantly inhibit the proliferation of liver cancer cells and induce apoptosis, showing anti-inflammatory properties, and having significant inhibition effects on inflammatory markers such as NF-κB, COX2, iNOS, and TNF-α." (PMID 37959658, 2023). "The rG7S-MICA had a high affinity with the antibody and could effectively enrich NK cells to the tumor-bearing site of liver cancer in nude mice, and could enhance the anti-tumor activity by promoting the release of IFN-γ and TNF-α from NK cells via the MICA-NKG2D/Fc-FcR pathway." (PMID 32075046, 2020). "Moreover, although deletion of BAK significantly inhibited hepatocyte apoptosis in Mcl-1 knockout mice, deletion resulted in reduced incidences of liver cancer, reduced TNFα production, oxidative stress and oxidative DNA damage in non-cancerous livers." (PMID 30404157, 2018). "Experiments both in vitro and in animal models of liver cancer have demonstrated that, compared with conditioned medium from untreated and single-factor treatment groups, conditioned medium from MSCs pretreated with IFN-γ and TNF-α significantly promoted invasion by liver cancer cells." (PMID 24502410, 2014). "Although the direct effect of TNFα upon PNCs has not been explored in zebrafish models of tumour initiation, the latter mechanism is more likely since no signs of leukocyte-mediated cell death have been recorded and TNFα positive macrophages promote tumourigenesis in zebrafish liver cancer models." (PMID 32325966, 2020). "The mice that received DEN injections demonstrated significant elevations in serological markers of liver cancer, angiogenesis, and proinflammatory cytokines, including AFP, DCP, VEGF, and TNF-α (All P < 0.001), compared to the negative control group." (PMID 41602133, 2025). "By contrast, anti-CD4–anti-PD1 treatment did not reduce the incidence of liver cancer, the NAFLD activity score (NAS), or the number of TNF-expressing hepatic CD8+ or CD8+PD1+CXCR6+ T cells." (PMID 33762733, 2021).
lymphopenia (146 papers, 2012 to 2026). Reduction in the number of lymphocytes. "A sustained inflammatory response driven by a ‘cytokine storm’, including the release of pro-inflammatory cytokines (TNF-α, IL-6, IL-8 and IL-10) and lymphopenia, is thought to be a major cause of life-threatening complications in SARS-CoV-2 patients." (PMID 36313994, 2022). "In vitro, cortisol reduces mRNA levels of IL-1β, TNF-α, and IL-8, as well as IL-2 serum levels, causing lymphopenia during acute stress." (PMID 36425123, 2022). "The macrophage infections promote the production of proinflammatory cytokines including TNF-α (tumor necrosis factor-alpha), which can cause bystander apoptosis in lymphocyte populations, leading to immunosuppression and lymphopenia." (PMID 35363588, 2022). "Cytokine storm is a phenomenon of excessive inflammatory reaction and has been associated with lymphopenia, with greater levels of inflammatory markers (TNF alpha and Interleukin 6 [IL-6]) causing more lymphocyte death." (PMID 34912430, 2021). "This leads to defective antigen presentation and lymphopenia, which causes the defective function of lymphoid cells, whereas monocytes remain potent and keep producing TNF-α and IL-6." (PMID 33673529, 2021). "Hyperinflammation may cause lymphopenia by inducing apoptosis, pyroptosis (both due to prolonged secretion of TNF-α, IL-6 or IL-18), or PANoptosis (due to the synergistic effect of IFNγ and TNF-α)." (PMID 39896810, 2024). "This refers to an increase in pro-inflammatory cytokines such as TNFα and IL-6 which might have a role in lymphopenia caused by T cell apoptosis." (PMID 37484181, 2023). "Lymphopenia and elevated neutrophil count suggest an alteration of lymphocyte function and are associated with elevated secretion of IL-6 and TNF-alpha, since these inflammatory markers contribute to lymphocyte apoptosis as well as decreased proliferation of lymphocytes." (PMID 34454452, 2021). "It was also reported that elevated serum levels of TNF‐α and IL‐6 were negatively correlated with the total T‐cell count in severe cases of COVID‐19, indicating the potential involvement of these cytokines in lymphopenia and T‐cell loss." (PMID 32935333, 2021). "In this respect, corticosteroids, TNF-α-blockers, and IL-6-blockers should be preferably used over other immunosuppressive agents that may cause severe lymphopenia." (PMID 33207589, 2020). "However, it has been suggested that tumor necrosis factor-alpha and interleukin-1 act as cytotoxic factors and their high expression is implicated in lymphopenia." (PMID 22373449, 2012). "Interestingly, CD4+ lymphopenia in PB has been associated with resistance to conventional immunosuppressant such as corticosteroids and methotrexate but responsive to treatment with TNF-α inhibitors." (PMID 37161980, 2023). "Similarly, SARS-CoV-2 triggers release of IL-6, TNF, IL-10, and PD-1 from alveolar macrophage, which may contribute towards and compound ongoing cytokine storm, causing lymphocytopenia." (PMID 35883618, 2022). "Neutrophilia is driven by cytokines like IL-6 and TNF-α, while lymphopenia results from chronic immune activation and apoptosis." (PMID 40337399, 2025). "In severe cases, lymphopenia and excessive proinflammatory cytokines such as interleukin (IL)-1β, IL-6, and tumor necrosis factor (TNF)-α were observed in line with the activation of innate and adaptive immunity." (PMID 36944716, 2023). "Crosstalk between monocytes and lymphocytes possibly involving the TNF pathway and Fc-γ receptors, as well as other features of innate immunity were the most likely dysregulated pathways involved with lymphopenia." (PMID 36311769, 2022).